RHOC (ras homolog family member C)
Diseases named in the same sentence as RHOC in open-access papers (continued):
Sharing a sentence is not in itself a finding about the gene and the disease.
cancer (continued). "We then investigated how RhoC affects the interaction of cancer cells with ECs." (PMID 25677806, 2015). "These mutually exclusive alterations at the signaling upstream of RHOC in several different cancers suggest that activation of RHOC could be one of the major downstream effects of driver alterations." (PMID 25887147, 2015). "It is possible that the depletion of RhoC sensitizes cancer cells to apoptotic signals induced by NK cells, which could explain the reduced levels of RhoC‐depleted cells compared to control cells in the lung at 24 h after injection." (PMID 25677806, 2015). "Our data suggest that ROCK1 and ROCK2 might act downstream of RhoC to regulate cancer cell adhesion to and transmigration across ECs." (PMID 25677806, 2015). "RhoC also regulates the extension of protrusions made by cancer cells on vascular ECs in vivo." (PMID 25677806, 2015). "RhoC was one of several Rho GTPases that we found to regulate adhesion of cancer cells to ECs." (PMID 25677806, 2015). "We therefore investigated how RhoC affects different steps of cancer cell: EC interaction." (PMID 25677806, 2015). "Here we investigate the role of RhoC during cancer cell interactions with ECs in vitro and in vivo." (PMID 25677806, 2015). "We report here that RhoC is important for cancer cell interaction with ECs during TEM, which could explain its central role in metastasis." (PMID 25677806, 2015). "This suggests that the defect in spreading on ECs due to RhoC depletion might reduce cancer cell retention in the lungs." (PMID 25677806, 2015). "Last, our study suggests that targeting ROCK signaling, which is a shared downstream mediator of both RhoA and RhoC, may be sufficient to block K-Ras-driven cancer as has been previously suggested." (PMID 26030593, 2015). "High expression levels of RhoC correlate with clinical cancer metastasis." (PMID 25677806, 2015). "We demonstrate that RhoC is important for cancer cell‐EC 7interactions and could thereby contribute to metastasis." (PMID 25677806, 2015). "Thus, a significant number of studies in a wide range of cancers strongly suggest an important role of RhoC in cancer metastasis." (PMID 24533098, 2014). "It is unclear whether RhoC is subjected to any posttranscriptional regulation in the carcinoma cells." (PMID 25188245, 2014). "Among these, RhoC has been identified as an especially important player in metastasis, and its expression correlates with metastatic spread of various types of carcinomas." (PMID 25236186, 2014). "The expression of RhoA and RhoC is frequently induced in human cancers." (PMID 23382905, 2013). "In addition, we show that RhoC over-expression decreases cancer cell adhesion and, in turn, accelerates cellular body movement and focal adhesion turnover, especially, on fibronectin-coated surfaces." (PMID 24312560, 2013). "RhoA and RhoC have reciprocal roles in controlling cancer cell motility." (PMID 24224016, 2013). "RHOC-induced cytoskeletal changes and the release of vascular permeability factors function cooperatively to mediate cell intravasation during the early stages of cancer cell metastasis." (PMID 22895562, 2012). "This will be helpful in elucidating the role of RhoC in regulating proliferation of cancer cells." (PMID 23145020, 2012). "Interestingly, RhoC was recently described to regulate invadopodia in cancer cells, which are closely related to podosomes in myeloid cells." (PMID 22916134, 2012). "RhoC GTPase is expressed in several cancers and promotes metastasis." (PMID 21776386, 2011). "A combined strategy in targeting both HGF and RhoC may be an attractive option in cancer therapies, an area that is under active investigation." (PMID 29147173, 2010). "In HCT116 cells, the multiple shRNAs expression constructs could efficiently and simultaneously induce inhibition of RhoA and RhoC genes and markedly inhibit the invasion and migration potentials of cancer cells." (PMID 19374769, 2009).
cancer (continued). "Recent accumulating evidences have shown that RhoA and RhoC are over-expressed in many kinds of cancers, and they may play important roles in initiation and progression of cancers." (PMID 19374769, 2009). "In addition, BASP1-AS1, RHOC and SLC39A1 have been reported to be associated with cancer." (PMID 37239411, 2023). "Therefore, biphasicity may result from the peak in RhoC stimulation that promotes cancer cell survival and spread." (PMID 35354476, 2022). "We assess the hypothesis that RhoC amplifies interferon signaling and thereby increases junction dysregulation, consequently promoting cancer cells’ motility and invasiveness; this work supports inhibition of RhoC as a potential therapeutic strategy in aggressive cancers." (PMID 34513691, 2021). "However, according to current research, RhoC itself does not seem to mutate, but rather promotes cancer metastasis through its overexpression." (PMID 34627249, 2021). "Additionally, RhoC promotes a cancer stem cell (CSC) phenotype in HNSCC." (PMID 32915198, 2020). "In this study, we showed that the combination of biomarkers demonstrated a better prognostic value than either one of Pin1, RhoA or RhoC, suggesting that these factors act together in the cancer metastatic process and thus effect of downregulation of one factor could be compensated by the others." (PMID 31324164, 2019). "Of note, we did not perform luciferase reporter assays (ie, using constructs containing the 3'UTR sequence of RhoC or a mutant version thereof) as an additional approach to confirm that RhoC is a target of miR‐138 because this has already been shown in other studies using cancer cells." (PMID 30828688, 2019). "While we focused mostly on the use of a modified MYXV we were able to show that the effects of F11 on MYXV growth in cancer cells could be mimicked through the use of pharmacological inhibition or siRNA-mediated silencing of key regulators of cortical actin (RhoA, RhoC, mDia1, or LIMK2)." (PMID 24391902, 2013). "Moreover, some reports showed that down-regulating the expression of RhoA and RhoC using small interfering RNA (siRNA) approaches may inhibit the proliferation and invasiveness of cancer cells." (PMID 20828398, 2010). "This evidence supports the role of RhoC in OSCC cells as an oncogene and is consistent with previous studies in a variety of cancer types and is supported by relevant clinical studies." (PMID 33519932, 2021). "We will focus in particular on five members of the RHO GTPase family, including RHOA, RHOB, RHOC, RAC1, and CDC42, to illustrate the role of lncRNAs in cancer progression." (PMID 34771549, 2021). "In this review, we will explore the relationships between VEGFs, their receptors, and the Rho GTPases, highlighting the involvement of RhoA, RhoC, and RhoG in VEGF signaling and the formation of new blood vessels in cancer." (PMID 32377503, 2020). "Conversely to RHOA and RHOC, RHOB has been described to be downregulated in several malignancies where its expression promotes apoptosis in cancer cell lines and inhibits invasion." (PMID 31888022, 2019). "RhoC can stimulate the expression of MMP2, which promotes cancer cell invasion and metastasis through degradation of the extracellular matrix." (PMID 28818073, 2017). "Several studies have defined the targets of miR-138 such as VIM, RhoC, Hif-1α, CCND1 and Sirt1 in cancer types other than RCC, which are often involved in cell migration, EMT, DNA damage repair, senescence." (PMID 28978010, 2017).
cancer (continued). "Overall, we show the ability of miR-10b to activate the expression of c-Jun through RhoC and NF1, which represents a novel pathway for promoting migration and invasion of human cancer cells." (PMID 27494896, 2016). "In glioblastoma cells, miR-10b-HOXD10 regulation axis and its downstream effectors, RHOC, uPAR and MTA-MMP also mediated invasiveness of cancer cells." (PMID 25614041, 2015). "This study is the first of its kind to establish the involvement of RhoC in STAT3 phosphorylation and hence in promoting the activation of core cancer stem cells (CSCs) transcription factors." (PMID 24533098, 2014). "The 2Chr7:1n,1d cells exhibited a more invasive phenotype by expressing higher levels of the pro-invasive genes (IGFBP2, PDGFRA, RHOC, FOXM1, and PLAU) and matrix metalloproteinase 2 (MMP2), all of which are well-reported for cancers, including GBM." (PMID 24282558, 2013). "In the present research, we studied the influence of RhoC and different structures of IQGAP1 on cancer cell proliferation and cell cycle related proteins." (PMID 23145020, 2012). "RhoB, RhoC and ROCK-1 mRNA levels were significantly higher in ccRCC tissues compared with non-cancer tissues." (PMID 21119662, 2011). "The aim of this study is to investigate the functions of PRL-3 and RhoC in the migration of A549 cell and the potential mechanism of PRL-3 and RhoC in carcinogenesis and cancer development." (PMID 21159255, 2010). "Some reports indicate that RhoA, RhoC and their downstream target ROCK are needed for cancer cell extravasation." (PMID 20822528, 2010). "In addition, RHOC, a ferroptosis and cuproptosis-related gene that affects the prognosis of AML, has a strong ability in predicting the OS of the cancer." (PMID 40173324, 2025). "Unlike other members of Rho family, like RhoA and RhoC, which play oncogenic roles, RhoB has been shown to suppress tumorigenesis in pancreatic and other cancers." (PMID 37794133, 2023). "Out of those four genes, three (RHOC, LZTS1, ARHGDIG) are known cancer genes." (PMID 34762640, 2021). "At present, anti-cancer research involving RhoC is not very extensive, possibly due to insufficient availability of detail concerning the mechanism of RhoC action in cancer metastasis." (PMID 34627249, 2021). "RhoA and RhoC induce multiple signaling pathways, including the PI3K/Akt pathway, mitogen-activated protein kinase kinase 1/2 (MEK1/2)/ERK1/2 pathway, and ROCK pathway in various cancer cells." (PMID 33406809, 2021). "Overall survival (OS) analysis indicated that patients with high RhoC expression had poorer OS than cancer patients with lower RhoC expression, but the difference was not statistically significant (P=0.281)." (PMID 33519932, 2021). "RhoC is a well-known oncogene that enhances the migration and invasive ability of cancer cells, and TNF-α increases the blood–brain barrier (BBB) permeability and penetration of cancer cells into the brain." (PMID 31900168, 2020). "For example, although these three Rho members similarly interact with Rho effectors thus far identified, RhoA, RhoB, and RhoC act on different effectors, namely ROCKi/2, integrins and formin FMNL3, respectively, and exert different functions in cancer cell migration and morphogenesis." (PMID 29749605, 2018). "This supports the role for RhoC in invasion by PC-3 cells and is consistent with the recent demonstration of a role for MKL implicating transcriptional outputs from the Rho pathway in invasion by certain aggressive cancers." (PMID 27600078, 2016). "However, to promote cancer activity, they also target different genes including C/EBPβ, FOXO1, NFI-A, STAT5A, ARTN, FBXW7, and SEPT6 (for miR-223) and FUS1, RhoC, PTEN, CDKN1A, TGFβR2, and NRF2 (for miR-93)." (PMID 26273679, 2015).
cancer (continued). "A number of research groups have demonstrated that miR-138 is not only involved in tumorigenesis but also regulating metastasis-related events such as migration and invasion by targeting several downstream genes including RhoC, HIF1α and SOX4 in different context of cancer cells." (PMID 25614041, 2015). "Even though RHOC alterations are not frequent in TCGA samples, its over-expression was previously shown to promote metastasis of cancer cells." (PMID 25887147, 2015). "In addition, RhoC is absent or expressed at very low levels in normal non-dividing cells, but cancer cells express RhoC at high levels." (PMID 40333248, 2025). "However, we found a number of established drivers of cancer progression and invasion (e.g., mTOR, STAT1/5, RHOC, ARF6, HMGB, and CRK) with increased expression levels as well as known suppressors (e.g., AIFL1 and SLIT3) with decreased expression levels upon PTEN inhibition." (PMID 36555834, 2022). "However, platelets detach from cancer cells approximately 6 h after their interaction, suggesting that RhoC does not act by regulating interactions of cancer cells with platelets." (PMID 25677806, 2015). "IDO and RhoC, both important in human cancer development and progression, were used as vaccine targets and 12 pigs were immunized with overlapping 20mer peptides spanning the entire porcine IDO and RhoC sequences formulated in CTL-inducing adjuvants: CAF09, CASAC, Montanide ISA 51 VG, or PBS." (PMID 26442104, 2015). "Therefore, we hypothesize that both RhoC and IQGAP1 may play important role in cancer cell transformation and proliferation and there is a potential association between them." (PMID 23145020, 2012). "Additionally, in contrast to RHOA and RHOC, RHOB localizes not only at the plasma membrane but also on endosomes, multivesicular bodies, and in the nucleus, which could contribute to its contrasting behaviors in cancer biology." (PMID 34771549, 2021). "We previously reported that RhoA depletion reduces cancer cell adhesion to ECs and delays cancer cell intercalation; however, RhoA depletion reduced cancer cell velocity on top of ECs before intercalation, which was not the case when RhoC or ROCKs were depleted." (PMID 25677806, 2015). "While the potential interaction between IFITM1 and RhoC-GTPase was not directly assessed in our study, it has been reported that Rho-GTPases can interact with caveolin 1 (CAV-1) in cancer cells." (PMID 26897526, 2016). "RhoC has recently been reported to affect cancer cell TEM, but the steps at which it regulates cancer cell interaction with ECs is not known." (PMID 25677806, 2015).
infection (3 papers, 2012 to 2017). The state of being infected such as from the introduction of a foreign agent such as serum, vaccine, antigenic substance or organism. "After lentiviral infection, RhoC knockdown clones were selected using Puromycin (1.6 μg/ml) antibiotic." (PMID 24533098, 2014). "To better understand the role of RhoC in CSC formation, we inhibited the RhoC function using RNAi coupled with lentiviral transduction and infection strategies to obtain stable RhoC knockdown clones." (PMID 24533098, 2014). "The inhibition of RhoC expression was carried out using small hairpin RNA (shRNA) and the lentiviral transduction and infection methodology as described in the methods section." (PMID 24533098, 2014). "Moreover, the activation of RhoC by an additional viral protein within the first few hours of infection might explain why F11 promotes very different phenotypes at early and late time points during infection." (PMID 28486133, 2017).
RHOC also shares sentences with these, for which no sentence is quoted: breast (3 papers); acute myeloid leukemia (2); colon adenocarcinoma (2); ductal carcinoma in situ (2); esophageal squamous cell carcinoma (2); renal carcinoma (2); Sepsis (2); squamous cell carcinoma (2); acute myocardial infarction (1); brain tumor (1); Cerebral ischemia (1); disc degeneration (1); esophageal carcinomas (1); inflammation (1); Lymphatic Metastasis (1); neurological diseases (1); pancreas (1); sarcoma (1); testis cancer (1); tetanus (1); Tongue (1); triple-negative breast carcinoma (1); urothelial cell carcinoma (1); virus infection (1).